DUSP4 (dual specificity phosphatase 4)
Description:
Regulates mitogenic signal transduction by dephosphorylating both Thr and Tyr residues on MAP kinases ERK1 and ERK2.
Synonyms: MKP-2; MKP2; HVH2; TYP
Tractability: PROTAC: ubiquitination databases record sites on it; a small molecule that binds it is known.
Target class: Phosphatase; Serine/threonine/tyrosine protein phosphatase; Enzyme; Protein Phosphatase
Gene: Protein-coding gene on chromosome 8 (29,333,064 to 29,350,684, reverse strand). Ensembl gene ENSG00000120875.
Subcellular location: Nucleus
Subcellular location (Human Protein Atlas): Nucleoplasm
Pathways (Reactome):
Signal Transduction: ERKs are inactivated; Negative regulation of MAPK pathway; RAF-independent MAPK1/3 activation
Gene Ontology:
Molecular function: MAP kinase serine/threonine phosphatase activity; phosphatase activity; protein binding; protein serine/threonine phosphatase activity; protein tyrosine phosphatase activity; protein tyrosine/threonine phosphatase activity; MAP kinase phosphatase activity; MAP kinase tyrosine/serine/threonine phosphatase activity
Biological process: dephosphorylation; negative regulation of ERK1 and ERK2 cascade; endoderm formation
Cellular component: nucleoplasm; nucleus
Genetic constraint (gnomAD): Loss-of-function variants: 13 observed, 25.6 expected, observed/expected ratio (o/e) 0.51, 90% interval 0.33 to 0.81. The upper end of that interval is the gene's LOEUF score, 0.81, which puts it in group 3 of 6, group 1 being the genes least tolerant of losing a copy. Missense variants: 448 observed, 529.19 expected, observed/expected ratio (o/e) 0.85, 90% interval 0.78 to 0.92. Synonymous variants: 257 observed, 232.06 expected, observed/expected ratio (o/e) 1.11, 90% interval 1 to 1.23.
Homologues: Orthologues: chimpanzee DUSP4 (99% identical), macaque DUSP4 (99% identical), guinea pig DUSP4 (97% identical), mouse Dusp4 (97% identical), rat Dusp4 (96% identical), pig DUSP4 (96% identical), dog DUSP4 (95% identical), rabbit DUSP4 (94% identical), tropical clawed frog dusp4 (81% identical), zebrafish dusp4 (68% identical). Paralogues in human: DUSP1 (60% identical), DUSP5 (45% identical), DUSP2 (40% identical), DUSP16 (29% identical), DUSP8 (29% identical), DUSP7 (28% identical), DUSP6 (27% identical), DUSP9 (27% identical), DUSP10 (27% identical), SSH2 (24% identical), SSH1 (24% identical), SSH3 (21% identical), and 19 more.
Diseases named in the same sentence as DUSP4 in open-access papers:
DUSP4 is named in the same sentence as 124 diseases in open-access papers, as found by Europe PMC text mining. Sharing a sentence is not in itself a finding about the gene and the disease. The quoted sentences say what the papers report.
breast carcinoma (49 papers, 2011 to 2025). "Gene and protein loss of DUSP4 was found in breast cancer tissues compared to matched normal breast tissues." (PMID 34679636, 2021). "TRIM24 has been associated with prognosis in breast cancer and over-expression of DUSP4 has been shown to improve the outcome of chemotherapy and overall survival." (PMID 33849068, 2021). "For example, the 2q35 and 5q11.2 breast cancer risk loci are considerably closer (≤100 kb) to corresponding promoter targets than 8p12 CCVs are to the DUSP4 promoter region, yet many restriction fragments at these loci have no observable promoter interaction." (PMID 31936698, 2020). "In our latest fine-mapping study, INQUISIT revealed seven target genes at the 8p12 breast cancer risk locus, of which only DUSP4 was a high confidence target." (PMID 31936698, 2020). "Downregulation of DUSP4 is associated with progression in several types of cancer, including colorectal cancer, breast cancer, pancreatic cancer and diffuse large B cell lymphoma." (PMID 29212207, 2017). "In contrast, DUSP4 acts as a tumour suppressor, with low expression associated with increased tumour grade, recurrence, and poor prognosis in breast cancer patients." (PMID 26859151, 2016). "Balko and colleagues found that the loss of DUSP4 activates MAPK pathways which in turn stimulates cancer stem cell-like phenotypes in basal-like breast cancer." (PMID 25929337, 2015). "Decreased expression of DUSP4 is associated with breast cancer drug resistance and increased expression of active ERK1,2." (PMID 25051360, 2014). "Using a genetically engineered mouse model, we generated mammary-specific Dusp4-deleted primary epithelial cells to investigate the necessary conditions in which DUSP4 loss may drive breast cancer oncogenesis." (PMID 35850776, 2022). "We reasoned that this lack of phenotype could be due to the luminal-like nature of the MMTV-Neu model, given that most examples of DUSP4 loss occur in basal-like breast cancer, which is substantially different in nature to that of luminal like disease." (PMID 35850776, 2022). "We found the first evidence that breast cancer risk variation at the 8p12 locus downregulates DUSP4 promoter activity and is negatively correlated with long-range chromatin looping interactions with the DUSP4 promoter region." (PMID 31936698, 2020). "Thus, the literature indicates that DUSP4 protein acts as a tumour suppressor in breast cancer, which is compatible with our finding of its negative regulation by a breast cancer risk allele." (PMID 31936698, 2020). "DUSP4 specifically is associated with increased resistance to targeted therapy against another EGFR family member, HER2, in breast cancer." (PMID 38212428, 2024). "Loss of DUSP4, with consequent activation of ERK and JNK pathways, increased the formation of mammospheres and the cancer stem cell population in basal-like breast cancer cell lines, and these effects were hampered by MEK inhibitors." (PMID 36358725, 2022). "Reduced expression of dual-specificity protein phosphatase 4 (DUSP4) due to promoter methylation is frequent in basal-like breast cancer." (PMID 36358725, 2022).
breast carcinoma (continued). "For example, miR-137 targeted dual specificity phosphatase 4 (DUSP4) in breast cancer to inhibit EMT and suppressed doxorubicin resistance." (PMID 34250246, 2021). "A lower concentration of DUSP4 was observed in breast cancer tissues compared to normal tissues, as well as in regions of colorectal cancer." (PMID 35008796, 2021). "In breast cancer cells, IL-4 exerts a wide spectrum of pro-tumorigenic effects by reducing expression of dual specificity phosphatase 4 (DUSP4), which negatively regulates ERK and p38 activity." (PMID 34769439, 2021). "It has been observed that DUSP4 expression was significantly up-regulated in breast cancer cell lines, and the miR-137 level was dramatically down-regulated." (PMID 34299149, 2021). "Arteaga and colleagues found that loss of dual specificity phosphatase-4 (DUSP4), a negative regulator of the MAPK pathway, promoted cancer stem cell-like phenotypes in basal-like breast cancer." (PMID 32391382, 2020). "Firstly, we performed 3C in normal and breast cancer cell lines to map chromatin interactions between PREs, containing CCVs, and the DUSP4 promoter region." (PMID 31936698, 2020). "DUSP4 knockdown enhances the formation of breast cancer stem cells and increases the invasive ability of estrogen receptor-positive breast cancer stem cells." (PMID 31936698, 2020). "Although Ras/MAPK activating mutations are rare in breast cancer, they can occur infrequently, and we and others have previously reported loss of Ras/MAPK negative regulators (DUSP4, NF1, RND1) in breast cancer as a mechanism of pathway activation." (PMID 32634121, 2020). "Györffy and colleagues correlated Herceptin resistant tumours from patients with DUSPs involved in development of Herceptin resistance in HER2 positive breast cancer, and suggested that DUSP4 is involved in this process." (PMID 29671404, 2018). "Applying in vitro gene silencing coupled with independent validation in clinical cohorts, we pinpointed DUSP4 as the most promising MKP correlated to trastuzumab resistance in HER2-positive breast cancer patients." (PMID 29100381, 2017). "Conversely, other studies indicated DUSP4 is downregulated and inhibits tumor development in colorectal cancer and breast cancer." (PMID 29212207, 2017). "Higher expression of DUSP4 was described in primary breast cancer, colorectal adenocarcinoma, pancreatic cancer, human melanoma cells, and as a result of chemical hepatocarcinogenesis in rats." (PMID 29100381, 2017). "RNAi-mediated DUSP4 depletion decreased proliferation in mouse mammary tumor cells both in vitro and in vivo." (PMID 29100381, 2017). "Intriguingly, DUSP4 knockdown resulted in inhibition of the active phosphorylation mark p300-1834p in our breast cancer cells, whilst protecting the repressive mark p300-89p." (PMID 26859151, 2016). "Taken together, these data indicate a novel chromatin-anchored role for DUSP1 and DUSP4 in mesenchymal breast cancer cells." (PMID 26859151, 2016). "DUSP4 expression is observed in various human cancers including breast cancer, colorectal cancer, pancreatic cancer, lung cancer, glioma, and malignant melanoma." (PMID 25688264, 2015). "A recent component which has been shown to be involved in breast cancer drug resistance is the phosphatase DUSP4 which removes the phosphate from active ERK1,2." (PMID 25051360, 2014). "In vitro experiments suggest that this is due to increased ERK activation, because expression of DUSP4/MKP-2 in breast cancer cell lines both reduced ERK activation and increased cell killing by docetaxel." (PMID 22812510, 2013). "Conversely, recent studies show that levels of DUSP4/MKP-2 correlate with drug resistance of residual disease in breast cancer patients following neo-adjuvant chemotherapy." (PMID 22812510, 2013).
breast carcinoma (continued). "Interestingly, in human breast cancer, DUSP4 deletion events are highly co-occurring with both of these lesions." (PMID 35850776, 2022). "Somatic and/or epigenetic DUSP4 loss of function (LOF) has been attributed to oncogenic function in EGFR-mutant non-small cell lung cancer, glioma, diffuse large B cell lymphoma and breast cancer." (PMID 35850776, 2022). "Indeed, several studies from our laboratory and others implicate DUSP4 loss in prolonged MAPK/ERK activation, particularly in highly aggressive subtypes of breast cancer, like basal-like breast cancers." (PMID 35850776, 2022). "Furthermore, the involvement of DUSP4 expression and chemoresistance has been shown to be positively correlated in gastric and breast cancers." (PMID 35008796, 2021). "Besides, up-regulation of DUSP4 in breast cancer cells partially abolished the chemo-resistance of miR-137 mimic." (PMID 34299149, 2021). "Recent studies have shown that DUSP4 protein is highly expressed in breast cancer and liver cancer." (PMID 32897241, 2020). "In primary breast cancer, MKP-2 / DUSP4 is expressed several times higher than normal tissues." (PMID 32897241, 2020). "Some studies have demonstrated DUSP4 is overexpressed and could promote progression in a number of cancers, including colorectal and breast cancer." (PMID 29212207, 2017). "DUSP4 is frequently lost in early-onset and high-grade breast carcinomas." (PMID 29100381, 2017). "In breast, DUSP4 acts also on ERK1/2 along with a breast cancer-related protein, DUSP6." (PMID 28603644, 2017). "Given that the key histone acetyltransferase p300 mediates acetylation of this mark, we speculated that DUSP4 may regulate p300 chromatin dynamics in the mesenchymal state in breast cancer cells." (PMID 26859151, 2016). "In a recent study, the loss of DUSP4, a downstream molecule in the TGF-β apoptosis signaling pathway, was shown to increase mammosphere formation and the expression of the CSC-promoting cytokines IL-6 and IL-8 in a mo- del of basal-like breast cancer (BLBC)." (PMID 24558636, 2013). "DUSPs such as DUSP1, DUSP4, and DUSP6 are involved in EMT and breast cancer stem cell (CSC) activity regulation." (PMID 41158869, 2025). "It has been shown that blocking autocrine and paracrine IL-4 signalling impairs breast cancer stem-like cell proliferation, invasion, and tumor growth by downregulating MAPK pathway activity through up-regulation of DUSP4." (PMID 41029387, 2025). "DUSP4 (MKP-2) can block the initiation of EMT program by inhibiting the activation of JNK signaling pathway, and restore the sensitivity of breast cancer cells to doxorubicin." (PMID 41211430, 2025). "The present study demonstrates DUSP4 promotes DOX resistance in GC, in agreement with findings in breast cancer." (PMID 29212207, 2017). "In basal-like breast cancers, especially in chemotherapy resistant triple negative breast cancer (TNBC), low DUSP4 mRNA is coupled with high RAS-ERK activation, that also relates to shorter recurrence free survival." (PMID 29100381, 2017). "DUSP1, DUSP4, and DUSP6 were constitutively expressed in both epithelial MCF-7 and mesenchymal MDA-MB-231 breast cancer cell lines." (PMID 26859151, 2016). "Several DUSP family members are thought to be involved in breast cancer metastasis including DUSP1, DUSP4, and DUSP6." (PMID 26859151, 2016).
breast carcinoma (continued). "Here we show that DUSP1, DUSP4, and DUSP6 are involved in epithelial-to-mesenchymal transition (EMT) and breast cancer stem cell (CSC) regulation." (PMID 26859151, 2016). "Treatment of MCF-7 breast cancer cells with doxorubicin can induce EMT, and DUSP4 knockdown partially abrogates this effect." (PMID 26859151, 2016). "Knockdown of DUSP1, DUSP4, and DUSP6 involved in the formation of CD44hi/CD24lo/EpCAM+ breast CSCs, and importantly DUSP1 knockdown reduces CSC formation, while DUSP4 and DUSP6 knockdown enhance CSC formation, suggesting that DUSPs modulate EMT and CSC regulation in breast cancer differentially." (PMID 41158869, 2025). "Moreso, relevant research indicated that dual specificity phosphatase 4 could be a viable target resistance inhibition and regulating the EMT during breast cancer treatment." (PMID 39593959, 2024). "Although the association between 8p deletion and expression of DUSP4 in RCC has not been studied, loss of 8p was associated with downregulation of DUSP4 in breast cancer and EGFR-mutant lung adenocarcinoma." (PMID 34679636, 2021). "In breast cancer, DUSP4 is not a cancer-related protein but it is situated in an influencer position according to all five databases." (PMID 28603644, 2017). "Enforced expression of DUSP4 reduced the CD44+/CD24− population in multiple BLBC cell lines in a MEK-dependent manner, limiting tumor formation, again underpinning the dual role of TGF-β in breast cancer." (PMID 24558636, 2013).
colorectal cancer (21 papers, 2014 to 2025). A primary or metastatic malignant neoplasm that affects the colon or rectum. "Previous studies revealed that the expression of DUSP4 was negatively associated with distant metastases in colorectal cancer." (PMID 35774798, 2022). "Clarification was done for the association between DUSP4 gene expression and clinical outcome in patients with colorectal cancer." (PMID 35057823, 2022). "They investigated the association between DUSP4 expression and clinical outcome in 212 patients with colorectal cancer." (PMID 25688264, 2015). "Decreased expression of DUSP4 is associated with advanced tumor stage, lymphatic and vascular invasion, and liver and lung metastases in colorectal cancer." (PMID 25027955, 2014). "Also consistent with this prediction, DUSP4 genomic loss has been associated with pancreatic tumor progression, and in some colorectal carcinomas, DUSP4 down-regulation leads to cell proliferation and invasiveness." (PMID 35580987, 2022). "DUSP4, a member of the dual specificity phosphatase family, is considered an oncogenic gene that has been shown to be associated with proliferation, migration, and tumorigenicity in esophageal squamous cell carcinoma, renal cell carcinoma, and colorectal cancer." (PMID 37324492, 2023). "LINC01315 was also found to be correlated with DPEP1, KRT23, ASCL2, AXIN2, and DUSP4 in colorectal cancer." (PMID 35470736, 2022). "Proliferation was similarly unaffected by DUSP4 knockdown, which contrasts with what has been observed in other cancer types, including colorectal cancer." (PMID 36576731, 2022). "The results demonstrate that down-regulation of DUSP4 is related to the liver and lung metastasis of colorectal cancer." (PMID 35470736, 2022). "In order to further probe the biological role of DUSP4 in colorectal cancer cells, DUSP4 expression was assessed in six selected cell lines, namely FHC, LOVO, SW480, SW620, HCT116, and DLD1." (PMID 32897241, 2020). "Meanwhile, DUSP4-related ubiquitin signaling pathway play a core role in colorectal cancer cell function." (PMID 32897241, 2020). "Firstly, we detected the expression of DUSP4 in colorectal cancer tissues and the paired normal tissues through online dataset, western blot, qRT-PCR, and immunohistochemical staining analysis." (PMID 32897241, 2020). "Higher DUSP4 expression of functional significance was observed in colorectal cancer tissues and cells." (PMID 32897241, 2020). "Meanwhile, DUSP4 can directly deubiquitinate and stabilize Smad4 protein, hence further promote proliferation and metastasis of colorectal cancer cells." (PMID 32897241, 2020). "In this study, we identified that DUSP4 expression was significantly higher in colorectal cancer tissues and cells than in normal tissues and cells." (PMID 32897241, 2020). "Meanwhile, western blot and qRT-PCR, as well as photochemical staining analyses both indicated that DUSP4 expression was significantly higher in colorectal cancer tissues than in the paired normal tissues." (PMID 32897241, 2020). "In summary, DUSP4 expression was higher in colorectal cancer tissues than in the paired normal tissues." (PMID 32897241, 2020). "Our work discussed the role of DUSP4 in regulating colorectal cancer cell migration and invasion in DUSP4 over-expressed HCT116 cells and DUSP4 knocked-down SW480 cells." (PMID 32897241, 2020). "The exact role of DUSP4 should be further investigated in colorectal cancer and DUSP4 role as a potential novel therapeutic target for colorectal cancer should be investigated in the further study." (PMID 25688264, 2015). "In contrast, in non-melanoma cell lines with BRAF mutation, DUSP4 silencing did not affect their growth (a glioma cell line and a colorectal cancer cell line)." (PMID 37946160, 2023).